SLC2A3 (solute carrier family 2 member 3)
Description:
Facilitative glucose transporter. Can also mediate the uptake of various other monosaccharides across the cell membrane. Mediates the uptake of glucose, 2-deoxyglucose, galactose, mannose, xylose and fucose, and probably also dehydroascorbate. Does not mediate fructose transport. Required for mesendoderm differentiation (By similarity).
Synonyms: GLUT3
Tractability: Small molecule: a structure with a bound ligand is known; a high-quality ligand is known. Antibody: UniProt places it where antibodies can reach, with high confidence; its Gene Ontology location is reachable by antibodies, with high confidence; UniProt predicts a signal peptide or a membrane-spanning region; the Human Protein Atlas places it where antibodies can reach. PROTAC: ubiquitination databases record sites on it; its protein half-life has been measured; a small molecule that binds it is known.
Target class: SLC superfamily of solute carriers; Electrochemical transporter; SLC02 family of hexose and sugar alcohol transporters; Transporter
Gene: Protein-coding gene on chromosome 12 (7,919,230 to 8,019,007, reverse strand). Ensembl gene ENSG00000059804.
Subcellular location: Cell membrane; Perikaryon; Cell projection
Subcellular location (Human Protein Atlas): Plasma membrane
Pathways (Reactome):
Immune System: Neutrophil degranulation
Metabolism: Vitamin C (ascorbate) metabolism
Transport of small molecules: Cellular hexose transport
Gene Ontology:
Molecular function: D-glucose binding; D-glucose transmembrane transporter activity; dehydroascorbic acid transmembrane transporter activity; fructose transmembrane transporter activity; galactose transmembrane transporter activity; protein binding; transmembrane transporter activity
Biological process: D-glucose import across plasma membrane; D-glucose transmembrane transport; fructose transmembrane transport; galactose transmembrane transport; transport across blood-brain barrier; carbohydrate metabolic process; dehydroascorbic acid transport; L-ascorbic acid metabolic process; transmembrane transport
Cellular component: extracellular exosome; membrane; plasma membrane; ficolin-1-rich granule membrane; perikaryon; secretory granule membrane; specific granule membrane; tertiary granule membrane
Genetic constraint (gnomAD): Loss-of-function variants: 19 observed, 42.89 expected, observed/expected ratio (o/e) 0.44, 90% interval 0.31 to 0.65. The upper end of that interval is the gene's LOEUF score, 0.65, which puts it in group 2 of 6, group 1 being the genes least tolerant of losing a copy. Missense variants: 492 observed, 611.2 expected, observed/expected ratio (o/e) 0.8, 90% interval 0.75 to 0.87. Synonymous variants: 212 observed, 233.69 expected, observed/expected ratio (o/e) 0.91, 90% interval 0.81 to 1.02.
Homologues: Orthologues: chimpanzee SLC2A3 (99% identical), macaque SLC2A3 (97% identical), zebrafish slc2a3b (60% identical), Drosophila melanogaster sut1 (34% identical), Caenorhabditis elegans fdgt-1 (34% identical), Drosophila melanogaster CG7882 (34% identical), zebrafish slc2a11l (33% identical), tropical clawed frog slc2a11.2 (32% identical), Drosophila melanogaster sut2 (32% identical), zebrafish slc2a9l1 (31% identical), Drosophila melanogaster sut3 (28% identical), Caenorhabditis elegans hmit-1.3 (27% identical), and 36 more. Paralogues in human: SLC2A14 (95% identical), SLC2A1 (64% identical), SLC2A4 (57% identical), SLC2A2 (51% identical), SLC2A5 (39% identical), SLC2A7 (39% identical), SLC2A9 (35% identical), SLC2A11 (33% identical), SLC2A13 (29% identical), SLC2A12 (27% identical), SLC2A8 (27% identical), SLC2A10 (24% identical), and 1 more.
Diseases named in the same sentence as SLC2A3 in open-access papers:
SLC2A3 is named in the same sentence as 207 diseases in open-access papers, as found by Europe PMC text mining. Sharing a sentence is not in itself a finding about the gene and the disease. The quoted sentences say what the papers report.
colorectal cancer (45 papers, 2016 to 2026). A primary or metastatic malignant neoplasm that affects the colon or rectum. "A study pointed out that upregulation of SLC2A3 was associated with decreased OS and DFS in colorectal cancer patients, which indicated that SLC2A3 played an important role in the prognosis of CC patients." (PMID 37287923, 2023). "The SLC2A3 gene is also associated with a shorter survival time and a worse quality of life when it comes to colorectal cancer patients." (PMID 36046345, 2022). "SLC2A3 gene upregulation, which encodes glucose transporter 3, showed decreased disease-free survival in colorectal cancer patients." (PMID 35565690, 2022). "A study on colorectal carcinoma also underscored that upregulation of the SLC2A3 gene was associated with decreased overall and disease-free survival in patients with colorectal cancer, suggesting that determination of SLC2A3 expression might be useful for predicting the prognosis of these patients." (PMID 35957685, 2022). "In colorectal cancer, SLC2A3 expression positively correlates with CD4+ and CD8+ T-cell infiltration and modulates PD-L1 expression, thereby contributing to immune evasion." (PMID 41268544, 2025). "In colorectal cancer, low-glucose conditions trigger SLC2A3 expression through the AMPK/CREB1 pathway, promoting both glucose absorption and cell proliferation." (PMID 41268544, 2025). "For example, ITGA5 has been shown to ptomote the occurrence and development of colorectal cancer, SLC2A3 can promote macrophage infiltration by glycolysis reprogramming in gastric cancer." (PMID 36959648, 2023). "In colorectal cancer, SLC2A3 plays a crucial role in perineural invasion via the regulation of epithelial-mesenchymal transition." (PMID 36247875, 2022). "This is consistent with the results of a previous study; the analysis with global gene expression profiling of human colorectal cancer cell lines showed that the expression of SLC2A3 was positively correlated with CD4+ and CD8+ T cells." (PMID 35957685, 2022). "According to recent reports, SLC2A3 is a membrane transporter associated with EMT and immune characteristics in colorectal cancer, and its upregulation is associated with poor OS." (PMID 35865532, 2022). "For example, in individuals with colorectal cancer, increased SLC2A3 expression was related with decreased overall survival and disease-free survival, while increased SLC16A5 expression predicted increased survival in prostate cancer patients." (PMID 35518353, 2022). "High expression of solute carrier family 2 facilitated glucose transporter member 3 (SLC2A3) is closely associated with poor prognosis of papillary thyroid cancer and colorectal cancer." (PMID 33962639, 2021). "To clarify the expression and role of SLC2A3 in colorectal cancer (CRC), we analyzed the TCGA and GEO databases and found that SLC2A3 mRNA levels were significantly higher in CRC tissues than that in adjacent non-tumor tissues." (PMID 34211835, 2021). "It was observed that upregulation of the SLC2A3 genes is associated with decreased OS and DFS in colorectal cancer patients." (PMID 34422642, 2021). "Upregulation of the SLC2A3 genes is associated with decreased OS and DFS in colorectal cancer patients." (PMID 30943948, 2019). "Furthermore, SLC2A3 has been shown to influence colorectal cancer progression and head and neck squamous cell carcinoma by governing Epithelial-Mesenchymal Transition (EMT) and immune responses." (PMID 40824962, 2025). "Elevated SLC2A3 expression has been reported to correlate with adverse outcomes in tongue cancer, influences the epithelial-mesenchymal transition (EMT) in colorectal cancer, and is linked to detrimental TME changes, such as macrophage infiltration, in gastric and breast cancers." (PMID 38778609, 2025).
colorectal cancer (continued). "Energy stress or glucose deficiency in the TME activates adenosine monophosphate‐activated protein kinase (AMPK), which activates CREB1 (a proto‐oncogene) to induce GLUT3 expression in colorectal cancer cells by anchoring the CREB1 binding site on the SLC2A3 promoter." (PMID 39584783, 2024). "A previous study in colorectal cancer showed that SLC2A3 could regulate the epithelial–mesenchymal transition (EMT) classical pathway and PD-L1-mediated immune responses, which was consistent with our research results." (PMID 35957685, 2022). "However, overexpression of SLC2A3 was found in several cancers such as colorectal cancer, gastric cancer and breast cancer." (PMID 36247875, 2022). "Besides, SLC2A3 genes have been reported to exhibit high expression in patients with colorectal cancer." (PMID 33173535, 2020). "High SLC2A3 expression resulted in shorter OS and disease-free survival in colorectal carcinoma (CRC)." (PMID 36247875, 2022). "In colorectal cancer cells, SLC2A3 expression is regulated by the TGF-β/JNK/ATF2 signaling pathway, thus, increased SLC2A3 levels exacerbate the aggressiveness of colorectal cancer cells." (PMID 38778609, 2025). "Initially, our western blot analysis revealed a one-way regulatory relationship from SLC2A3 to TGF-β, echoing findings in colorectal cancer research by Li." (PMID 38625978, 2024). "Therefore, we identified SLC2A3 and ASNS as critical ferroptosis genes for JAT inhibition in colorectal cancer." (PMID 37710311, 2023). "In addition, SLC2A3, the gene of GLUT3, is upregulated in high mortality colorectal carcinoma patients based on the TCGA dataset." (PMID 31817208, 2019).
glioma (36 papers, 2010 to 2025). A benign or malignant brain and spinal cord tumor that arises from glial cells (astrocytes, oligodendrocytes, ependymal cells). "To determine SLC2A3-mediated effects of miR-106a on glioma cell proliferation, we first analyzed which genes were associated with cell proliferation and correlated with SLC2A3 expression in glioma." (PMID 24124917, 2013). "Meanwhile, we checked the expression of CAV1 with the key glycolysis pathway genes HK2 and GLUT3(SLC2A3) in gliomas and found that the expression of CAV1 is positively related to HK2 and GLUT3." (PMID 37642765, 2023). "Mechanistically, TRIM66-induced upregulation of GLUT3 protein was shown to be a result of the binding of c-MYC on SLC2A3/GLUT3 promoters in glioma cells." (PMID 36139694, 2022). "Real time PCR showed that the levels of SLC2A3 increased markedly in high grade gliomas in comparison to low grade gliomas and normal tissues (P < 0.05)." (PMID 24124917, 2013). "In our study, we also showed that SLC2A3 was over-expressed in high grade glioma tissues, and repression SLC2A3 abrogated miR-106a-mediated cell proliferation and glucose uptake in GBM cells." (PMID 24124917, 2013). "Interestingly, Xu and colleagues 2015 reported the striking findings of targeting SLC2A3 by siRNA-based nanomedicine in glioma therapy." (PMID 36902193, 2023). "From the transcriptome data analysis results in the public database, it was found that CDK4, PBK, ANGPTL2, TMEM100, and MEX3A were significantly up-regulated in the glioma samples compared with the normal samples, whereas NEGR1 and SLC2A3 were down-regulated in the glioma samples at the mRNA level." (PMID 36358948, 2022). "The correlation of miR-106a-5p and SLC2A3 has been demonstrated in human glioma, and inhibition of SLC2A3 by miR-106a attenuated cell proliferation, inhibited glucose uptake, and conferred a favorable survival for patients with glomerular basement membrane disease." (PMID 35957685, 2022). "We further explored the correlation between miR-106a and SLC2A3 expression in gliomas." (PMID 24124917, 2013). "It has been reported that CDK4 knockdown impedes the colony formation and cell proliferation of glioma, and that PBK and SLC2A3 could be a potential prognostic factor and therapeutic target for GBM treatment." (PMID 36358948, 2022).
glioblastoma (34 papers, 2010 to 2025). The most malignant astrocytic tumor (WHO grade IV). "In glioblastoma, high SLC2A3 expression maintains the stem-like phenotype by increasing glycolytic activity, diminishing temozolomide cytotoxicity and leading to poor clinical outcomes." (PMID 41268544, 2025). "In nutrient-deprived conditions, glioblastoma SCs also showed an upregulation of GLUT3 (also known as SLC2A3), a transporter with higher affinity for glucose than GLUT1, in order to preserve glycolysis and maintain stemness." (PMID 29991569, 2018). "Moreover, a decreased expression of miR-106a increased the expression of SLC2A3, thereby contributing to progression and poor prognosis in glioblastoma patients." (PMID 36497462, 2022). "Previous studies have shown that SLC2A3 could be directly regulated by miR-106a in glioblastoma, as well as by miR-195-5p in bladder cancer." (PMID 29867504, 2018). "Furthermore, the family member of SLC2A3, GLUT1, has been demonstrated to be involved in the lactylation of glioblastoma and is regulated by glucose metabolism driven by PERK." (PMID 41377071, 2025). "In line with this notion, several down-regulated genes are reported markers of glioblastoma CSCs including FABP7, TF and SLC2A3 (aka GLUT3), suggesting that knockdown of PIEZO1 may influence the maintenance of the cancer stem cell state 55,56." (PMID 40791371, 2025). "In order to further understand the relevance of elevated GLUT3 in GBM biology, we analyzed the Ivy Glioblastoma Atlas Project database and found GLUT3 (SLC2A3), but not GLUT1 (SLC2A1), expression was significantly elevated at the leading edge of GBMs." (PMID 33843470, 2021).
breast carcinoma (30 papers, 2007 to 2025). "Compared with normal tissues, SLC2A3, 4 and 14 were significantly downregulated in breast cancer." (PMID 34488531, 2021). "The correlation between upregulated SLC2A3 and decreased OS has been widely reported in other solid tumors, including CRC and breast cancer." (PMID 36902193, 2023). "SLC2A3 is up-regulated in a variety of tumors, such as CRC and breast cancer, and is involved in tumor progression and poor prognosis." (PMID 37621680, 2023).
gastric cancer (30 papers, 2012 to 2026). A primary or metastatic malignant neoplasm involving the stomach. "SLC2A3 was found to be highly expressed in tumor tissues and was associated with an unfavorable prognosis in patients with gastric cancer." (PMID 35957685, 2022). "In the TCGA dataset, survival analysis indicated that a high expression level of SLC2A3 was significantly associated with poor prognosis in patients with gastric cancer, both in overall survival (OS; p = 0.001) and disease-specific survival (DSS; p = 0.008)." (PMID 35957685, 2022). "This study aimed to explore the prognostic implications of SLC2A3 and its underlying immune mechanisms in gastric cancer." (PMID 35957685, 2022). "The T stages of patients were significantly different between the two groups (p = 0.002), suggesting that high SLC2A3 expression is associated with the T stage in patients with gastric cancer." (PMID 35957685, 2022). "We found that SLC2A3, as a ferroptosis marker, was highly expressed in gastric cancer tissues and was associated with poor prognosis in patients with gastric cancer, and it contributed through immune-related pathways." (PMID 35957685, 2022). "SLC2A3 could predict poor prognosis in gastric cancer, associated with macrophage infiltration in the tumor microenvironment (TME)." (PMID 36247875, 2022). "Therefore, based on these results, we inferred that a high SLC2A3 expression level leads to an unfavorable prognosis in gastric cancer, which might be associated with EMT." (PMID 35957685, 2022). "Similar results showed that miR-129-5p directly targets SLC2A3 to suppress glucose consumption, lactate generation, cellular ATP levels, and glucose uptake in gastric cancer cells." (PMID 36247875, 2022). "SLC2A3, a ferroptosis marker, was found to be highly expressed in gastric cancer, colon cancer, and other tumors." (PMID 35957685, 2022). "Understanding the roles of SLC2A3 and the relationship between ferroptosis and tumor immunity can provide valuable insights for treating patients with gastric cancer." (PMID 35957685, 2022). "In the univariate Cox regression analysis, SLC2A3 was found to be a poor prognostic factor for gastric cancer (hazard ratio: 1.777, 95% confidence interval: 1.269–2.487, p < 0.001), as well as age, TNM stage, pathologic stage, and residual tumor." (PMID 35957685, 2022). "Compared with adjacent normal tissues, SLC2A3 was highly expressed in gastric cancer, colon cancer, and other tumors (p < 0.05)." (PMID 35957685, 2022). "Univariate and multivariate Cox regression analyses indicated that SLC2A3 can be used as an independent prognostic factor for predicting the outcome in patients with gastric cancer." (PMID 35957685, 2022). "Inhibition of SLC2A3 by miR-129-5p suppresses glucose consumption in gastric cancer cells by regulating the PI3K-Akt and MAPK signaling pathways, suggesting that SLC2A3 is a potential therapeutic target for the treatment of gastric cancer." (PMID 35957685, 2022). "miR-129-5p inhibited the glycolysis and proliferation of gastric cancer cells by inhibiting the SLC2A3." (PMID 33173535, 2020). "Bioinformatics analysis and IHC staining were used to reveal the expression of SLC2A3 in gastric cancer and the correlation with survival prognosis." (PMID 33061855, 2020). "In our study, SLC2A3 was involved in the infiltration of M2 macrophages in BCa and contributed to the impaired anti-tumor immunity cycle, consistent with the findings of a gastric cancer study." (PMID 36902193, 2023). "In gastric cancer, SLC2A3 promotes infiltrating macrophages." (PMID 37189176, 2023). "In contrast, our research findings in gastric cancer suggested that there was a close relationship between SLC2A3 and miR-195-5p, indicating that the interaction of SLC2A3 and miR-195-5p might occur not only in bladder cancer but also in stomach cancer." (PMID 35957685, 2022). "Slc2a3 promotes glycolysis and provides energy for gastric cancer cell proliferation." (PMID 35634481, 2022).
gastric cancer (continued). "Similarly, in the multivariate Cox regression analysis, SLC2A3 was a poor prognostic factor for gastric cancer (hazard ratio: 1.624, 95% confidence interval: 1.086–2.430, p = 0.018), as well as age, pathologic stage, and residual tumor." (PMID 35957685, 2022). "This study aimed to determine the prognostic value of SLC2A3 expression in gastric cancer." (PMID 35957685, 2022). "SLC2A3 functions as a tumor promoter and accelerates aerobic glycolysis in gastric cancer cells, and it potentially contributes to the M2 subtype transition of infiltrating macrophages in the microenvironment of gastric cancer." (PMID 35957685, 2022). "For example, SLC2A3 could act as a biomarker to determine prognosis and immune infiltration in gastric cancer by mediating glycolysis reprogramming." (PMID 34276794, 2021). "However, whether SLC2A3 affects the prognosis of gastric cancer has not yet been systematically or elaborately elucidated." (PMID 35957685, 2022).
Hyperglycemia (29 papers, 2011 to 2026). An increased concentration of glucose in the blood. "It is therefore a plausible possibility that Slc2a3/Glut3–mediated glucose uptake is increased under conditions of hyperglycemia and that excess glucose uptake leads to changes in the visceral endoderm cells themselves." (PMID 35478964, 2022).